RB1 (RB transcriptional corepressor 1)
Diseases named in the same sentence as RB1 in open-access papers (continued):
Sharing a sentence is not in itself a finding about the gene and the disease.
retinoblastoma (continued). "As a consequence, it was suggested that MYCN amplifications and RB1 mutations were mutually exclusive and that N-MYC dysregulation could provide an alternative pathway to malignancy in retinoblastomas." (PMID 33670346, 2021). "We also developed the tools to induce RB1 mutations in a wild-type human stem cell and produce retinoblastomas indistinguishable from those of patient-derived iPSCs." (PMID 34315877, 2021). "Medication for ovarian stimulation may cause hypermethylation of the RB1 gene promoter and this can partially explain the association between ART and retinoblastoma." (PMID 35087971, 2021). "Ex vivo research has shown that in humans, retinoblastoma may initiate from RB1-depleted cone precursors." (PMID 34003213, 2021). "Early attempts to model retinoblastoma in mice by mutating the Rb1 gene failed to produce retinal tumors in Rb+/– mice." (PMID 34315877, 2021). "The spectrum of phenotypic expression of heritable retinoblastoma includes incomplete penetrance, which is defined as the absence of retinoblastoma or retinoma in an adult who is heterozygous for a pathogenic RB1 allele." (PMID 33807189, 2021). "The retinoblastoma tumor suppressor, RB1, is an important cellular target of many PV E7 proteins." (PMID 34465025, 2021). "Few studies focus on using NGS for tumor specimens, in detecting mutations other than RB1 and no more than a dozen other genes known to occur in retinoblastoma, or in correlating these findings with clinic-histopathologic features." (PMID 33466343, 2021). "Two children with trilateral retinoblastoma carried a heterozygous constitutional RB1 variant, one was not tested." (PMID 33919815, 2021). "The CRISPR-Cas9 RB1 inactivation was intentionally left mosaic (<10% of cells) in the starting stem cell populations to more closely mimic the clonal heterogeneity in human retinoblastoma." (PMID 34315877, 2021). "Retinoblastoma is usually initiated by biallelic RB1 gene inactivation." (PMID 34680394, 2021). "ELTD1 showed high levels in Weri-Rb-1 cells and Rb tumors compared to fetal retina (Fetal retina versus Weri-Rb-1 cells: **p < 0.01; Fetal retina versus Rb tumors: ***p < 0.001; N = 8), but this significant difference did not extend to the aggressive Y79 cells." (PMID 33430814, 2021). "However, recent research has shown that the analysis of a particular type of DNA, known as cell-free DNA, within the eye fluid or blood of patients, can be used to detect changes in the RB1 gene or other parts of the genome within a retinoblastoma tumour." (PMID 33805427, 2021). "High MYCN amplification is proposed as a novel mechanism of disease initiation in retinoblastoma without RB1 mutation." (PMID 32824373, 2020). "We present two cases of a subtype of retinoblastoma, a rare ocular tumor in children, presenting without the typical mutation in the RB1 gene but showing amplification of the transcription factor MYCN frequently reported in pediatric malignancies." (PMID 32971811, 2020). "The THSD1 gene is often mutated in cancer and was found to be duplicated in a patient with unilateral retinoblastoma (1N13), lacking an RB1 mutation." (PMID 32577795, 2020). "This conflicts with human tumorigenesis where high MYCN amplification is proposed as a driver in a rare form of retinoblastoma without RB1 mutation." (PMID 32824373, 2020). "This proof of concept study demonstrates that plasma cfDNA analysis has the potential to detect somatic RB1 mutations in patients with advanced unilateral retinoblastoma without a detectable germline mutation." (PMID 32633890, 2020). "Furthermore, amplification of MYCN was identified in wild-type RB1 retinoblastomas, suggesting that amplification of this gene can trigger tumorigenesis in the background of a functional retinoblastoma protein." (PMID 33575207, 2020).
retinoblastoma (continued). "For example, it is now known that not all children afflicted with retinoblastoma are homozygous for the LOF RB1 allele and this condition has, in several cases, been associated with aberrant expression of unlinked regulatory genes." (PMID 32064050, 2020). "However, a recent study demonstrated that RB1 promoter methylation can act as the first ‘hit’ in rare cases of retinoblastoma." (PMID 32224912, 2020). "Which cell type is the origin of retinoblastoma, why such cells are so vulnerable to malignant transformation when RB1 is lost, and how the disease progresses are the outstanding questions that must be answered to ultimately benefit designing targeted therapies." (PMID 32824373, 2020). "Together, these data suggest that HELLS overexpression (or persistent expression) may contribute to the maintenance of a de-differentiated and proliferative state in Rb1/p107-null retinae that may result in retinoblastoma formation." (PMID 32071286, 2020). "Our findings suggest that MYCNOS1 knockdown is a potential therapeutic strategy for MYCN-amplified retinoblastoma without RB1 mutation." (PMID 33270844, 2020). "Further, almost all retinoblastomas have RB1 gene inactivation." (PMID 32071286, 2020). "A few years ago, we elucidated how tumors progress quickly following RB1 inactivation, showing that while the retinoblastoma genome is stable – with RB1 being the only known tumor suppressor gene mutated – multiple cancer pathways can be deregulated epigenetically." (PMID 32426419, 2020). "The RB1 gene is highly penetrant with most carriers presenting with retinoblastoma before age five." (PMID 33194895, 2020). "Non-hereditary retinoblastoma comprises the majority of cases (60%) with both RB1 alleles locally mutated in the affected retina." (PMID 32824373, 2020). "Interestingly, retinoblastoma samples share a common miRNA expression profile, and some mRNA targets of these miRNAs include RB1, as well as other tumor suppressor genes." (PMID 31973216, 2020). "Together, these results suggest that MYCNOS1 maintained the cone signature in MYCN-amplified retinoblastoma without RB1 mutation." (PMID 33270844, 2020). "A mouse model of MYCN-amplified retinoblastoma without an RB1 mutation is generated by conditionally overexpressed MYCN in retinal cells with wildtype Rb1, but the tumors do not develop." (PMID 32824373, 2020). "Our first goal in this study was to establish if the variant FGFR4 p.Gly388Arg may be another primary mechanism in the formation of retinoblastoma other than the RB1 gene." (PMID 33456465, 2020). "A limitation of this study is the small sample size and that the sample included extremely rare cases of MYCN-amplified retinoblastoma without RB1 mutation." (PMID 33270844, 2020). "Most retinoblastomas are caused by biallelic mutations in the RB1 gene, with non-germline cases being caused by two somatic hits, and inherited cases caused by an initial germline hit and a further somatic hit." (PMID 30745306, 2019). "Genetic factors that are responsible for retinoblastoma are not all yet identified in patients who do not have the RB1 gene mutations." (PMID 31207142, 2019). "Epimutation of the RB1 gene was recently found in a six generations retinoblastoma family." (PMID 31497535, 2019). "A very rare and aggressive subset of unilateral, non-heritable retinoblastoma can result from highly amplified MYCN in the setting of normal RB1 alleles." (PMID 31835688, 2019). "The der(X) region harboring the RB1 gene was inactivated in a subset of somatic cells, including the retinal cells, in the patient subject which acted as the first hit in the development of her retinoblastoma." (PMID 31806026, 2019). "Determining how loss of pRB changes cells is important for expanding our treatment options for patients with Retinoblastomas, and may provide insights into how RB1 contributes to additional tumor types." (PMID 31058073, 2019).
retinoblastoma (continued). "We next assessed whether the der(X) region had been subjected to XCI, which could inactivate RB1 and nearby genes leading to the retinoblastoma and other symptoms observed in the patient." (PMID 31806026, 2019). "The child was treated by enucleation of the retinoblastoma-containing eye (homozygous non-germline RB1 mutation) and is being monitored annually." (PMID 30223826, 2018). "Given that our understanding of how RB1 loss in vitro or in model organisms changes the LINC expression profile is limited, determining how RB1 homozygote mutation affects LINC levels in a complex and developmentally disorganized Retinoblastoma tumor represents a real challenge." (PMID 29868118, 2018). "Lastly, most children (>70%) with retinoblastoma do not have germline mutations in RB1 and exhibit the unilateral subtype." (PMID 29533992, 2018). "Previous studies have shown that loss of E2f1 and E2f3, but not E2f5, prevents retinoblastoma formation in Rb1-deficient mice." (PMID 30220967, 2018). "In addition to primary tumors, we also verified the results in retinoblastoma cell lines (Y79, Weri-Rb1, and SO-Rb50), demonstrating that UHRF1 is highly expressed at both protein and transcript levels." (PMID 28467809, 2017). "This makes inactivation of RB1 by gene mutation or its protein product, pRb, by protein phosphorylation, a necessary condition for initiating retinoblastoma tumorigenesis, independent of MYCN amplification." (PMID 28211617, 2017). "However, RB1+/+MYCNA retinoblastomas have distinctive histological features with undifferentiated cells with large prominent, multiple nucleoli, necrosis, apoptosis and little calcification." (PMID 29124525, 2017). "This led to the hypothesis that high level MYCN amplification is sufficient for initiation of tumorigenesis of RB1+/+ retinoblastoma." (PMID 28211617, 2017). "A small, but unique subgroup of retinoblastoma has been identified with no detectable mutation in the retinoblastoma gene (RB1) and with high levels of MYCN gene amplification." (PMID 28211617, 2017). "Based upon the ‘two-hit theory’ (known as the Knudson hypothesis), retinoblastoma originally paved the avenue leading to better understanding of tumor-suppressor genes, which was confirmed by the discovery of the RB1 gene." (PMID 28358317, 2017). "In a cohort of 1068 retinoblastoma patients, Gallie and co-workers identified a subset of 29 patients (2.7%) with no detectable mutation in RB1, where 52% of these had MYCNA." (PMID 29124525, 2017). "The majority of non-heritable retinoblastoma (95%) is also caused by bi-allelic inactivation of RB1 but in this case occurring through two subsequent somatic events in the developing retina." (PMID 27126562, 2016). "Germline methylation of the RB1 gene promoter was studied in a particular pedigree of six generations from the paternal side, with incomplete penetrance and bias towards healthy male carriers and those affected with unilateral retinoblastoma." (PMID 26753011, 2016). "Besides the well-established driver genes RB1 (13q-loss) and MYCN (2p-gain) we identified CRB1 and NEK7 (1q-gain), SOX4 (6p-gain) and NUP205 (7q-gain) as novel retinoblastoma driver candidates." (PMID 27115612, 2016). "In non-hereditary retinoblastoma, both RB1 mutations are somatic and occur in the same retinal cell that develops into a tumor." (PMID 26925970, 2016). "In contrast, the retinoblastoma showed enrichment of INDELs in both rb1 (80%) and rbl1 (74%) loci." (PMID 27739525, 2016). "Subsequent studies have documented methylation of the 5′ region of the RB1 gene in retinoblastoma." (PMID 26753011, 2016). "This indicates that post-mitotic human cone precursors are sensitive to RB1-depletion and may represent cell-of-origin for retinoblastoma." (PMID 27486389, 2016). "Since retinoblastoma is a rare disease and identified genetic events beyond RB1 inactivation appear to be rare except for large SCNAs, identification of mutually exclusive events might be challenging." (PMID 27126562, 2016).
retinoblastoma (continued). "This genetic pattern is supportive of the 2-hit hypothesis of tumorigenesis, similar to that of the retinoblastoma 1 (RB1) gene alterations for the development of retinoblastoma." (PMID 31093340, 2016). "We then studied 6 Rb patients with a large RB1 deletion of known parental origin." (PMID 26925970, 2016). "As a result, when the RB1 c.1981C>T/p.Arg661Trp mutation is inherited from the mother, loss of the contralateral paternal allele in the tumor would switch off MED4 expression and prevent retinoblastoma development in the context of a low penetrance mutation." (PMID 26925970, 2016). "Consistently, high levels of survivin were found in the RB1-null cancer retinoblastoma." (PMID 26160835, 2015). "In addition, ovarian germ cell tumors have been reported to arise in some women with retinoblastoma disease, suggesting a potential tumor suppressor role of Rb1 in the ovary." (PMID 26176933, 2015). "Early studies in the 1990s implicated Rb in cell adhesion by uncovering non-functional adherens junctions in osteosarcomas, retinoblastomas, and small-cell lung carcinomas, which are characterized by high frequencies of mutations in RB1." (PMID 26555075, 2015). "The initiating genetic lesion in retinoblastoma is RB1 gene inactivation." (PMID 26628093, 2015). "A much larger analysis will be required explore the spectrum of genomic lesions that contribute to retinoblastoma initiation in the absence of RB1 gene mutation." (PMID 24509483, 2014). "One of the goals of our study was to explore the relationship between MYCN amplification and RB1 inactivation to determine if a subset of retinoblastomas can be driven by a single oncogenic lesion (MYCN amplification) without RB1 loss." (PMID 24509483, 2014). "Furthermore, over-expression of miR-17-92 clusters with deletion of Rb1 and Rbl1 accelerated the emergence of retinoblastoma with frequent metastasis to the brain in mice." (PMID 25359779, 2014). "However, one of the challenges with identifying retinoblastomas driven exclusively by MYCN amplification is excluding all possible mechanisms of RB1 gene inactivation including SNVs, indels, LOH, deletions, translocations and promoter hypermethylation." (PMID 24509483, 2014). "Our data suggest that a significant proportion of retinoblastomas (3/10) thought to have wild type RB1 may actually have gene inactivation by chromothripsis." (PMID 24509483, 2014). "It is initiated in most cases by mutation of both alleles of the RB1 gene, the first tumor suppressor gene to be cloned, although some retinoblastomas initiate without RB1 mutation." (PMID 24901248, 2014). "RB1 inactivation confers limitless replicative potential to retinoblasts and these preneoplastic cells can progress to retinoblastoma by acquiring additional cellular properties including evasion of cell death and senescence, sustained angiogenesis and activation of growth-signaling pathways." (PMID 23765217, 2013). "Those individuals in family #1 who inherited the mutant RB1 allele from their mother displayed a similar level of nonsense and wild-type RB1 transcripts, and only one of eight carriers developed retinoblastoma." (PMID 23820649, 2013). "In 1971, Knudson revealed, utilizing statistical analyses of the retinoblastoma incidence data, that two hits in an “anti-oncogene” are the rate-limiting steps in this disease; this gene was later identified as the tumor suppressor RB1." (PMID 23840359, 2013). "Patient 1 developed Rb by sequentially developing unique mutations in each RB1 allele and did not appear to contain either mutation in the germ line." (PMID 23826078, 2013).
retinoblastoma (continued). "In contrast, RB1+/+ retinoblastoma tumors show low ARF mRNA." (PMID 22336108, 2012). "These RB1+/+ retinoblastomas show no detectable mutations in the RB1 gene and express full-length pRB protein." (PMID 22336108, 2012). "The Retinoblastoma 1 gene RB1 on chromosome 13 regulates cell growth and proliferation in the brain and other organs, and the suppression of both copies of this gene is associated with an embryonic neoplasm of retinal origin called retinoblastoma." (PMID 22536904, 2012). "A small percentage (approximately 5%) of unilateral retinoblastoma patients with no family history of the disease develop contralateral retinoblastomas despite having negative blood leukocyte tests for RB1 mutations." (PMID 22550413, 2012). "Biallelic RB1 gene inactivation is the initiating genetic lesion in retinoblastoma." (PMID 22916154, 2012). "Furthermore, these mutants provide a non-murine vertebrate model of rb1 and offer new potential for identifying the elusive retinoblastoma cell of origin and further insight into the developmental role of rb1." (PMID 23209449, 2012). "In humans, germline or somatic mutations occur throughout the 180 kb genomic region spanning the rb1 gene, including its promoter region, exons, and intronic essential splice sites, resulting in bilateral or unilateral retinoblastomas within the first 2 years of life." (PMID 23209449, 2012). "The remaining 60% of RB1 non-intermediary germline mutations often present as sporadic cases of unilateral retinoblastoma, without family history of retinoblastoma." (PMID 21615945, 2011). "The penetrance in this family is 4/11 (36%) among the available members and none of them has bilateral retinoblastoma, which is indicative of low expressivity for the germline RB1 c.1906 G>T mutation." (PMID 21615945, 2011). "The father of the index case (III-10), a 48-year old man, had the inherited RB1 p.V654L mutation, but without any suspicious clinical symptoms of retinoblastoma." (PMID 21615945, 2011). "We identified a novel constitutive mutation in the 5' UTR of the RB1 promoter region (g.2056C>G), in position – 4 with respect to the initial translation ATG codon in an infant, born after IVF, and affected with bilateral retinoblastoma." (PMID 19640284, 2009). "E2f1, rather than other E2fs, may be a potential target for novel therapeutics to prevent retinoblastoma in RB1+/− humans." (PMID 17608565, 2007). "Retinoblastomas form due to the inactivation of the RB1 gene together with other genetic changes." (PMID 17163992, 2006). "To more efficiently target chemotherapy to retinoblastoma and move away from broad-spectrum agents, we need to answer three fundamental questions: what is the disease's cell-of-origin, how does it expand, and what genetic events occur after RB1 inactivation?" (PMID 16231976, 2005). "In addition to the childhood tumour retinoblastoma, RB1 inactivation has also been demonstrated in a variety of tumours including sarcomas, lung, breast, and bladder carcinomas, as well as malignant gliomas." (PMID 12556968, 2003). "This is supported by findings indicating that retinoblastoma cells exhibit various elements of the cone precursor signaling circuitry, relying on it for their proliferation and survival, as well as the proliferation induced by RB1 knockdown in human cone precursors." (PMID 40317918, 2025). "It is necessary to mention that the authors of this study support that their results are exported from a small sample because of the rarity of retinoblastoma and that all participants in their study did not possess germline RB1 gene mutations but had a familial background of retinoblastoma." (PMID 41150792, 2025). "Despite its low incidence, retinoblastoma has provided crucial insights into human tumorigenesis, notably the two-hit mechanism of tumor-suppressor gene inactivation, which involves a mutation in both alleles of the RB1 gene." (PMID 40395327, 2025).